NDC80 (NDC80 kinetochore complex component)
Description:
Acts as a component of the essential kinetochore-associated NDC80 complex, which is required for chromosome segregation and spindle checkpoint activity. Required for kinetochore integrity and the organization of stable microtubule binding sites in the outer plate of the kinetochore. The NDC80 complex synergistically enhances the affinity of the SKA1 complex for microtubules and may allow the NDC80 complex to track depolymerizing microtubules. Plays a role in chromosome congression and is essential for the end-on attachment of the kinetochores to spindle microtubules.
Synonyms: HsHec1; HEC; HEC1; KNTC2; hsNDC80; TID3
Tractability: Small molecule: a structure with a bound ligand is known. PROTAC: ubiquitination databases record sites on it.
Gene: Protein-coding gene on chromosome 18 (2,571,520 to 2,616,635, forward strand). Ensembl gene ENSG00000080986.
Subcellular location: Nucleus; Chromosome, centromere, kinetochore
Subcellular location (Human Protein Atlas): Nuclear speckles; Nucleoplasm; Centrosome; Cytosol
Pathways (Reactome):
Cell Cycle: Amplification of signal from unattached kinetochores via a MAD2 inhibitory signal; EML4 and NUDC in mitotic spindle formation; Mitotic Prometaphase; Resolution of Sister Chromatid Cohesion; Separation of Sister Chromatids
Signal Transduction: RHO GTPases Activate Formins
Gene Ontology:
Molecular function: identical protein binding; kinetochore adaptor activity; microtubule binding; protein binding; cyclin binding
Biological process: attachment of mitotic spindle microtubules to kinetochore; attachment of spindle microtubules to kinetochore; centrosome duplication; chromosome segregation; establishment of mitotic spindle orientation; G2/MI transition of meiotic cell cycle; metaphase chromosome alignment; mitotic spindle organization; positive regulation of mitotic cell cycle spindle assembly checkpoint; spindle assembly involved in female meiosis I; mitotic cell cycle; mitotic sister chromatid segregation; mitotic spindle assembly checkpoint signaling; chromosome organization
Cellular component: centrosome; kinetochore; membrane; Ndc80 complex; nuclear speck; nucleoplasm; outer kinetochore; chromosome, centromeric region; cytosol; nucleus; cytoplasm
Genetic constraint (gnomAD): Loss-of-function variants: 33 observed, 50.39 expected, observed/expected ratio (o/e) 0.65, 90% interval 0.5 to 0.88. The upper end of that interval is the gene's LOEUF score, 0.88, which puts it in group 3 of 6, group 1 being the genes least tolerant of losing a copy. Missense variants: 360 observed, 499.06 expected, observed/expected ratio (o/e) 0.72, 90% interval 0.66 to 0.79. Synonymous variants: 156 observed, 172.55 expected, observed/expected ratio (o/e) 0.9, 90% interval 0.79 to 1.03.
Homologues: Orthologues: chimpanzee NDC80 (99% identical), macaque NDC80 (99% identical), dog NDC80 (93% identical), pig NDC80 (92% identical), guinea pig NDC80 (91% identical), rabbit NDC80 (89% identical), rat Ndc80 (85% identical), mouse Ndc80 (84% identical), tropical clawed frog ndc80 (57% identical), zebrafish ndc80 (44% identical), Caenorhabditis elegans ndc-80 (20% identical).
Diseases named in the same sentence as NDC80 in open-access papers:
NDC80 is named in the same sentence as 67 diseases in open-access papers, as found by Europe PMC text mining. Sharing a sentence is not in itself a finding about the gene and the disease. The quoted sentences say what the papers report.
breast carcinoma (22 papers, 2011 to 2025). "To further investigate the association between the NDC80 complex and cell growth in tumor cells, we utilized siRNAs targeting NDC80 to knock down its expression in two breast cancer cell lines, BT-549 and MCF-7." (PMID 39513104, 2024). "NDC80 has an important role in other cancers, such as liver and breast cancer, but it is rarely reported in GBM." (PMID 36238156, 2022). "This analysis indicates that the mRNA levels of multiple mitotic regulators, including TTK, Nek2, PLK1, Cyclin B1, BUB1, Aurora kinases A and B, and NDC80 (also known as HEC1) are elevated in breast cancers in NHB women." (PMID 36494865, 2022). "Poorly differentiated breast cancer tumors are characterized by specific set of over-expressed genes (e.g., UBE2C, CCNB2, CDK1, KIF2C, NDC80, and CCNB2) and are associated with more aggressive tumors and lower survival." (PMID 34300003, 2021). "Intriguingly, our data revealed that PTTG family members regulate breast cancer progression via the cell cycle, in which KIFs and NDC80 also highly participate, highlighting the value of this family in further research." (PMID 33173433, 2020). "Aberrant expression of NDC80 has been reported in several other tumors, for instance osteosarcoma, hepatocellulcar carcinoma, colorectal cancer and breast cancer, indicating its potential as a newly bio target." (PMID 32795325, 2020). "Moreover, knockdown of NDC80 significantly suppressed cell growth and inhibited the G1-S phase transition in two breast cancer cell lines." (PMID 39513104, 2024). "Interestingly, a few studies have shown that NDC80 is associated with PI3K/AKT, but the core component of its complex, SPC24, is defined to regulate the PI3K/AKT pathway in breast cancer cells and produce oncogenic effects." (PMID 37240068, 2023). "Additionally, CENPE, TOP2A, CENPF, TTK, and NDC80 are highly expressed in the cell cycle of basal-like breast cancer." (PMID 35496042, 2022). "Furthermore, breast cancer patients with both Ndc80 and Nek2 overexpression display shorter survival compared to patients with only either Ndc80 or Nek2 overexpression." (PMID 25557589, 2015). "The most common breast cancer subtype is Luminal A; NHB women with Luminal A breast cancers significantly overexpress PLK1, AURKB, and NDC80, while TBK1 is significantly overexpressed in Luminal A breast cancers from NHW women." (PMID 36494865, 2022). "Cluster 2 (KIF2C, NDC80, NUF2) is also in agreement with the molecular subtypes and has the expression pattern similar to Cluster 1 in breast cancer patients." (PMID 31260503, 2019). "TYMS is also a target gene of three Breast cancer drugs (Fluorouracil, Gemcitabine and Capecitabine) and physically interacts with two genes from the Triple Negative pattern -NUF2 and NDC80." (PMID 26892392, 2016). "NDC80 might be a good targeting option in suppressing breast cancer tumor growth, and dual targeting of NEK2 and NDC80 might improve the prognosis." (PMID 33109182, 2020). "To address whether our observations in mammary epithelial cells are translated into breast cancers, we performed TCGA analysis on selected SAC proteins, including BubR1, NDC80, Sgo1, and Mps1/TTK in relation to E2Fs genes using cBioPortal." (PMID 29100415, 2017).
glioma (12 papers, 2015 to 2024). A benign or malignant brain and spinal cord tumor that arises from glial cells (astrocytes, oligodendrocytes, ependymal cells). "In this study, we sought to explore the function of HEC1 (highly expressed in cancer 1) in glioma; a component of the NDC80 complex in glioma is crucial in the regulation of kinetochore." (PMID 39021287, 2024). "The identified DryNB included seven genes (KIF2C, CCNA2, NDC80, KIF11, KIF23, ANLN and CENPM) that were significantly associated with drug sensitivity or resistance of glioma patients to the targeted therapies." (PMID 31682596, 2019). "The clinical data verified the association of the identified genes (i.e., KIF2C, CCNA2, NDC80, KIF11, KIF23, ANLN, and CENPM) with the targeted therapy response and prognosis of glioma patients." (PMID 31682596, 2019). "As expected, treatment with siRNAs (AURKA siRNA2 and NDC80 siRNA3) significantly decreased the Ki-67 expression and the malignant proliferation of glioma cells." (PMID 26468983, 2015). "Knockdown of AURKA and NDC80 by siRNAs suppressed Ki-67 expression and proliferation of gliomas cells." (PMID 26468983, 2015). "Moreover, analysis of genes and proteins that interact with KIF18A showed that several molecules related to cell cycle and cell division, such as RRP7A, ANAPC4, WEE1, CDC20, and NDC80, were enriched in glioma." (PMID 35591854, 2022). "Interestingly, the expression level of NDC80 in glioma cells (U251, U-87MG, and A172) was significantly higher than that in normal astrocytes (HA 1800)." (PMID 36238156, 2022). "NDC80 independently predicts survival, but its role in glioma is unknown." (PMID 36635757, 2023). "In summary, this study has revealed the role of NDC80/HEC1 in the process of glioma development and in the tumor microenvironment of glioma." (PMID 39021287, 2024). "Bioinformatics analysis revealed that cNDC80, a new circRNA that has not been previously investigated in glioma, is generated by circularization of exons 14 to 17 of the NDC80 gene." (PMID 36635757, 2023). "In addition, we found several hub genes with worse OS and higher expression level in glioma patients, including VEGFA, NDC80, TIMP1, SAA1, CENPA, CENPF, and NCAPG and we firstly found relationship of SAA1, TIMP1, and molecular pathology in GBM." (PMID 30867991, 2019). "We then tested whether the temporal patterns of the prioritized 5 genes (i.e., KIF2C, CCNA2, NDC80, KIF11 and KIF23) could be used to predict drug sensitivities of different glioma cell lines." (PMID 31682596, 2019). "However, knockdown of AURKA (or NDC80) did not affect the NDC80 (or AURKA) expression in glioma cells." (PMID 26468983, 2015).
hepatocellular carcinoma (11 papers, 2017 to 2024). A malignant tumor that arises from hepatocytes. "It has also been suggested that high NDC80 complex expression is correlated with worse survival in hepatocellular carcinoma patients." (PMID 38102624, 2023). "In previous studies, Erb-B2 receptor tyrosine kinase 2 (ERBB2) and NUF2 component of the NDC80 Kinetochore Complex (NUF2) were reported to be biomarkers of hepatocellular carcinoma (HCC) recurrence after surgery." (PMID 34956309, 2021). "Bioinformatics analysis revealed that NDC80 and PBK can serve as biomarkers for HBV-associated hepatocellular carcinoma." (PMID 34917088, 2021). "Knockdown of NDC80 expression using shRNA inhibited the proliferation of hepatoma cells transcribed with the HBV genome." (PMID 32775402, 2020). "High levels of CDCA1 (also known as NUF2, NDC80 kinetochore complex component), KNTC2 (kinetochore associated 2), SPC24, and SPC25 have been found to be correlated with colorectal and hepatocellular carcinoma tumors." (PMID 29029446, 2017). "The NDC80 complex is composed of four components, comprising NDC80, NUF2, SPC24, and SPC25, and aberrant expression of these four components may cause uncontrolled cell proliferation in hepatocellular carcinoma." (PMID 38102624, 2023). "It has been reported that elevated NDC80 expression may participate in promoting the progression of human hepatocellular carcinoma, and it also leads to poor prognosis in osteosarcoma patients." (PMID 33816217, 2021). "Up-regulating expression level of NDC80 was negatively correlated with OS and positively correlated with immune infiltration cells, including regulatory T cells (Treg) and macrophages M0 in patients with hepatocellular carcinoma 34, which was consistent with the results of this study." (PMID 35813478, 2022). "SPC25 is a crucial component of NDC80, and its role in hepatocellular carcinoma (HCC) has been explored recently." (PMID 33408271, 2020).
lung carcinoma (10 papers, 2010 to 2022). "The results showed that the expression of NDC80 was positively associated with the levels of ATG7 in lung cancer, using the GSE102287 and GSE8894 datasets." (PMID 36105209, 2022). "In summary, in this study, we identified that NDC80 might be a diagnostic and prognostic indicator in lung cancer." (PMID 36105209, 2022). "The expression of NDC80 was significantly increased in lung cancer tissues, as compared to normal tissues, and high expression levels of NDC80 were correlated with unfavorable survival rates." (PMID 36105209, 2022). "In the present study, we screened NDC80 as a potential biomarker involved in radioresistance development in lung cancer cells using isobaric tags for relative and absolute quantitation (iTRAQ) analysis and the cancer genome atlas (TCGA) database." (PMID 36105209, 2022). "We confirmed that NDC80 is expressed at high levels in the LUAD and LUSC samples, and is associated with poor prognosis in lung cancer patients." (PMID 36105209, 2022). "Collectively, these results suggest that the downregulation of NDC80 improved the sensitivity of lung cancer cells to IR." (PMID 36105209, 2022). "Several reports obtained using bioinformatic analysis have shown that high expression levels of NDC80 resulted in poor survival in lung cancer patients." (PMID 36105209, 2022). "The NDC80 complex comprises NDC80 (Hec1 in humans), NUF2, spindle pole body component 25 (SPC25) and SPC24, among which SPC25 was recently found upregulated in lung cancer and associated with carcinogenesis, cancer cell growth and metastasis." (PMID 30408771, 2018). "Our data provide a novel prospect of using NDC80 for the regulation of radioresistance and suggest that NDC80 could be used as a novel therapeutic target for improving the sensitivity toward radiation therapy in lung cancer." (PMID 36105209, 2022). "In this study, we showed that NDC80 served as a prognostic indicator of lung cancer." (PMID 36105209, 2022). "Our findings suggest that NDC80 promotes the development of lung cancer by regulating autophagy, and might serve as a potential target for increasing the therapeutic sensitivity of lung cancer." (PMID 36105209, 2022). "To further investigate whether NDC80 was involved in radioresistance development in lung cancer cells, we determined the expression of NDC80 in A549 and H1246 parental and IR-resistant cells." (PMID 36105209, 2022). "All these results suggest that NDC80 might become a potential biomarker for the treatment of lung cancer." (PMID 36105209, 2022). "Moreover, we verified that NDC80 promoted cell growth and radioresistance in IR-resistant lung cancer cells by targeting autophagy." (PMID 36105209, 2022). "Furthermore, an in vitro analysis showed that the stable knockdown of NDC80 decreased the cell viability and increased therapeutic sensitivity in two lung cancer cell lines, A549-IRR and H1246-IRR." (PMID 36105209, 2022). "In this study, we screened differentially expressed genes using isobaric tags for relative and absolute quantitation (iTRAQ) analysis and datasets from the cancer genome atlas database, and found that nuclear division cycle 80 (NDC80) might act as a novel prognostic indicator of lung cancer." (PMID 36105209, 2022). "The downregulation of NDC80 inhibited the formation of autophagosomes, and reduced the expression of autophagy-related proteins such as LC3II, Beclin-1, and p62 in lung cancer cells." (PMID 36105209, 2022). "The result revealed an really interesting fact that even in different sub types of lung cancer (LUAD and LUSC), NDC80 and MAD2L1 shared biological functions." (PMID 32795325, 2020).
colon cancer (8 papers, 2011 to 2024). "With all hub genes, except NDC80, they also show high sensitivity and specificity in colon cancer." (PMID 39045407, 2024). "Irregular expression of NDC80 in cells is often accompanied with abnormal spindle checkpoint, abnormal chromosome separation and cell cycle disorders, and it has been found to lead to, and be highly expressed in, colon cancer cells." (PMID 33975549, 2021). "NDC80 promoted the proliferation and metastasis of colon cancer cells." (PMID 29246203, 2017). "In colon cancer, all hub genes showed high sensitivity and specificity, except NDC80, which was not present in the data set (right)." (PMID 39045407, 2024).
colorectal cancer (8 papers, 2019 to 2022). A primary or metastatic malignant neoplasm that affects the colon or rectum. "High expression of NDC80 promotes the malignant progression of colorectal cancer." (PMID 35456460, 2022). "Studies have shown that NDC80 is overexpressed in colorectal cancer, pancreatic cancer and gastric cancer, which may play a crucial role in carcinogenesis." (PMID 31788359, 2019).
pancreatic cancer (8 papers, 2017 to 2024). "NDC80 has also been associated with the HCC progression, and NDC80-knockdown in pancreatic cancer inhibited cell cycle and cell proliferation." (PMID 36317111, 2022). "Overexpression of NDC80 was correlated with prognosis of pancreatic cancer and regulated cell cycle and proliferation." (PMID 30598639, 2018). "NDC80 overexpression was correlated with the prognosis of pancreatic cancer and regulated cell proliferation." (PMID 29246203, 2017).
lung adenocarcinoma (7 papers, 2020 to 2023). A carcinoma that arises from the lung and is characterized by the presence of malignant glandular epithelial cells. "Prior to the present study on CENPA and NDC80, multiple studies have reported that these two factors were associated with poor prognosis of patients with lung adenocarcinoma, osteosarcoma, or other tumors." (PMID 32090084, 2020). "This study focuses on the effects of NDC80 complex genes on clinical features and prognosis in lung adenocarcinoma (LUAD)." (PMID 32226507, 2020). "NDC80, CENPL, ORC1, CENPN, CCNE1, and CCNB2 were significantly upregulated in the TCGA cohort as well as in the 18 pairs of lung adenocarcinoma patient samples, and high expression was significantly associated with poor prognosis in lung adenocarcinoma." (PMID 37123398, 2023). "Immunohistochemistry assay results revealed that both NDC80 and ATG7 were upregulated in an array of lung adenocarcinoma samples, compared to normal tissues, and the expression of NDC80 was identified to be positively associated with the levels of ATG7." (PMID 36105209, 2022). "Further, multivariate cox regression analysis identified NDC80 and MAD2L1 as independent prognostic indicators in lung adenocarcinoma (LUAD) and squamous cell carcinoma (LUSC) respectively." (PMID 32795325, 2020). "The expression profile of NDC80 and MAD2L1 was analyzed in various tumors using GEPIA and we discovered that both NDC80 and MAD2L1 were broad-spectrum up-regulated in multiple human tumors including lung adenocarcinoma and lung squamous cell carcinoma." (PMID 32795325, 2020).
osteosarcoma (7 papers, 2011 to 2022). A usually aggressive malignant bone-forming mesenchymal neoplasm, predominantly affecting adolescents and young adults. "In a study on osteosarcoma, it was pointed out that RFC3, CDK1, MAD2L1, NDC80, BUB1, etc. jointly participated in the related links of the disease prognosis of osteosarcoma." (PMID 35483337, 2022).
cervical cancer (5 papers, 2018 to 2024). A primary or metastatic malignant neoplasm involving the cervix. "Through its N‐terminus‐modification, NDC80 can be even utilized to inhibit proliferation and induces apoptosis of cervical cancer cells." (PMID 29341479, 2018). "By contrast, NDC80 and CAPG are a novel targets in the survival of cervical cancer." (PMID 36723760, 2023). "Hierarchical clustering and Gepia results indicated that the expression quantity of hub genes NDC80, TIPIN, MCM3, MCM6, POLA1, and PRC1 may determine the prognosis of cervical cancer." (PMID 33816217, 2021).
breast tumors (4 papers, 2010 to 2017). "Also, E2F1, E2F2, E2F3, Mps1/TTK, BubR1, NDC80 (HEC1), Nek2, and Sgo1 significantly co-overexpress in breast tumors." (PMID 29100415, 2017). "Interestingly, Bièche and his team (2011) reported that the mRNA expressions of NDC80 and AURKA were simultaneously higher in breast tumors than in the normal tissues." (PMID 26468983, 2015).